BTNL8 (butyrophilin like 8)
Description:
May stimulate primary immune response. Acts on T-cell stimulated sub-optimally through the TCR/CD3 complex stimulating their proliferation and cytokine production.
Synonyms: FLJ21458; BTN9.2
Tractability: Antibody: its Gene Ontology location is reachable by antibodies, with high confidence; UniProt predicts a signal peptide or a membrane-spanning region.
Gene: Protein-coding gene on chromosome 5 (180,899,077 to 180,952,164, forward strand). Ensembl gene ENSG00000113303.
Subcellular location: Membrane
Pathways (Reactome):
Immune System: Butyrophilin (BTN) family interactions
Gene Ontology:
Molecular function: protein binding; signaling receptor binding
Biological process: extrathymic T cell selection; regulation of cytokine production; T cell receptor signaling pathway
Cellular component: external side of plasma membrane; plasma membrane; membrane
Genetic constraint (gnomAD): Loss-of-function variants: 22 observed, 35.7 expected, observed/expected ratio (o/e) 0.62, 90% interval 0.44 to 0.88. The upper end of that interval is the gene's LOEUF score, 0.88, which puts it in group 3 of 6, group 1 being the genes least tolerant of losing a copy. Missense variants: 524 observed, 629.02 expected, observed/expected ratio (o/e) 0.83, 90% interval 0.77 to 0.89. Synonymous variants: 202 observed, 244.17 expected, observed/expected ratio (o/e) 0.83, 90% interval 0.74 to 0.93.
Homologues: Orthologues: chimpanzee BTNL8 (97% identical), macaque BTNL8 (78% identical). Paralogues in human: BTNL3 (69% identical), BTNL9 (34% identical), BTN1A1 (32% identical), BTN2A1 (31% identical), BTN2A2 (31% identical), BTN3A3 (31% identical), BTN3A1 (31% identical), ERMAP (27% identical), BTNL2 (19% identical), BTN3A2 (17% identical), CD276 (15% identical), MOG (14% identical), and 3 more.
Diseases named in the same sentence as BTNL8 in open-access papers:
BTNL8 is named in the same sentence as 22 diseases in open-access papers, as found by Europe PMC text mining. Sharing a sentence is not in itself a finding about the gene and the disease. The quoted sentences say what the papers report.
celiac disease (5 papers, 2021 to 2023). An autoimmune genetic disorder with an unknown pattern of inheritance that primarily affects the digestive tract. "Individuals with celiac disease exhibit a loss of BTNL8 expression concomitant with a loss of Vγ4+Vδ1+ IELs, but elimination of dietary gluten can restore BTNL8 expression." (PMID 37309673, 2023). "Interestingly, recent studies in patients with celiac disease have demonstrated a reduction in BTNL3/BTNL8 expression following acute episodes of inflammation, with an associated loss of the physiological normal gamma/delta T-cell subset of gut intraepithelial lymphocytes." (PMID 36300623, 2022). "Second, it was reported that whereas decreased BTNL3 and ablated BTNL8 expression in celiac disease could renormalise, this did not correlate with renormalisation of either intestinal Vγ1+ cells or TRGV4 reads, which is also consistent with other factors contributing to the cells’ dysregulation." (PMID 37708268, 2023).
colon cancer (5 papers, 2016 to 2023). "Although there is little known about the functional role of BTNL3, its downregulation was reported in colon cancer alongside BTNL8." (PMID 32375678, 2020). "BTNL8 gene is involved in immune response as it stimulates cytokine production and is also altered in intestinal inflammation and colon cancer." (PMID 29703154, 2018). "The modulation of other BTN/BTNL molecules such as BTNL3/BTNL8 seems also of interest in other pathologies such as colon tumors or autoimmune diseases." (PMID 30050536, 2018). "Indeed, HNF4G expression, not HNF4A, correlated with BTNL3/BTNL8 expression and γδ T-cell infiltration into tumors in our human colon cancer dataset." (PMID 37309673, 2023).
inflammatory bowel disease (4 papers, 2017 to 2025). A spectrum of small and large bowel inflammatory diseases of unknown etiology. "Given the known association of BTNL8 with inflammatory bowel disease severity, it is believed that BTNL8 may play a role in regulating intestinal inflammation seen in MIS-C." (PMID 41347066, 2025). "The recently discovered role of BTNL3 and BTNL8 for shaping Vγ4 γδ T cells in the human gut might be relevant for the loss of mucosal barrier function in inflammatory bowel diseases." (PMID 28649364, 2017).
Crohn disease (3 papers, 2023 to 2024). A gastrointestinal disorder characterized by chronic inflammation involving all layers of the intestinal wall, noncaseating granulomas affecting the intestinal wall and regional lymph nodes, and transmural fibrosis. "Moreover, CD103+Vγ4+cell dysregulation and loss were also displayed by humans with germline BTNL3/BTNL8 hypomorphism, which we identified as a risk factor for penetrating Crohn’s disease." (PMID 37708268, 2023). "Indeed, a common hypomorphic variant allele fusing BTNL8 and BTNL3 is associated with disease-modifying exacerbation of Crohn’s disease, consequent to dysregulation of gut Vγ4+ cells." (PMID 39576310, 2024).
breast carcinoma (1 paper, 2022). "BTNL2, BTNL3, BTNL8, BTNL9, and SKINTL constitute the BTNL family, which regard as a tumor inhibitor in many cancers, such as malignant melanoma and breast cancer." (PMID 36034784, 2022).
cervical cancer (1 paper, 2020). A primary or metastatic malignant neoplasm involving the cervix. "Four of these genes were also significantly up-regulated in cervical cancer cell lines (SiHa and C33A):EIF3K (p = 0.0092), RACK1 (p = 0.0086), TAPBPL (p = 0.0011) and BTNL8 (p = 0.0012)." (PMID 32025240, 2020).
COVID-19 (1 paper, 2024). A disease caused by infection with severe acute respiratory syndrome coronavirus 2. "As in many inflammatory diseases, including COVID-19, MIS-C has shown dysregulation of neutrophils which reportedly express BTNL8." (PMID 39576310, 2024).
enteropathy (1 paper, 2024). "The significant association of BTNL8 variant alleles with MIS-C might offer a link to enteropathy which is a common symptom of the disease." (PMID 39576310, 2024).
glioma (1 paper, 2022). A benign or malignant brain and spinal cord tumor that arises from glial cells (astrocytes, oligodendrocytes, ependymal cells). "Because the basal expression levels of BTN1A1, BTNL2, BTNL3, and BTNL8 were relatively low, in further analysis, we only focused on the expression of BTN2/3 subfamilies in pan-gliomas." (PMID 36033440, 2022).
intestinal tumors (1 paper, 2021). "In intestinal tumors, where BTNL8 was found to be downregulated, it can enhance the immune response mediated by T cells and plays a role in immune surveillance of tumor cells." (PMID 34221185, 2021).
melanoma (1 paper, 2022). A malignant, usually aggressive tumor composed of atypical, neoplastic melanocytes. "Additionally, based on the enrichment analysis in the Reactome pathway, we found that BTN family genes, such as BTNL8 and BTNL9, which play a vital role in the immune signaling pathway, were also obviously upregulated by NCTD in Vem-resistant melanoma." (PMID 36034784, 2022). "It has been reported that BTNL8 may be important for co-stimulation of primary immune response in the periphery at sites of inflammation, and BTNL9 can inhibit cancer aggression in melanoma cells." (PMID 36034784, 2022).
T cell deficiency (1 paper, 2023). "These considerations notwithstanding, our genetic analysis was still able to identify a significant association of BTNL3+BTNL8 / Vγ4+ T cell deficiency with penetrating CD." (PMID 37708268, 2023).
tumor (6 papers, 2021 to 2023). "Gene and pathway enrichment analysis revealed that the ‘Tumor_2’ population upregulates fucosylation, hydroxylation and HIF pathways, and genes associated with the basal-like tumor subtype (BTNL8, AGR3 and LYZ)." (PMID 35995947, 2022). "BTNL3 expression levels were higher in normal tissue than tumor tissue in both the datasets, whereas BTNL8 expression was only higher in normal tissue in the Skrzypczak dataset." (PMID 37309673, 2023). "We found that TENM1, FN1, and F12 are highly expressed in tumor tissue, while APOD and BTNL8 have a lower expression in tumor tissue." (PMID 34221185, 2021). "Both HNF4A and HNF4G were reduced in tumor tissue from both datasets, mirroring reduced BTNL3 and BTNL8 expressions in human tumors." (PMID 37309673, 2023). "We also found that the mRNAs of CD86 and BTNL8 were expressed in the siGPX4 group, suggesting that knocking down GPX4 increased T-cell activity and killed tumor cells." (PMID 37649598, 2023). "Analysis showed that expression levels of BTNL8 and BTNL9 were significantly lower in tumor tissues compared with that of normal tissues." (PMID 34635082, 2021). "We interrogated two human gene expression datasets, The Cancer Genome Atlas (TCGA) and Skrzypczak, to determine whether the expression levels of BTNL3 or BTNL8—homologs of mouse Btnl1 and Btnl6—were different between normal gut and tumor tissues." (PMID 37309673, 2023).
cancer (4 papers, 2013 to 2023). A tumor composed of atypical neoplastic, often pleomorphic cells that invade other tissues. "This suggests BTNL8 may be advantageous in cancer immunotherapy by potentially provoking polyclonal ‘effector-like’ T cell responses, which have been associated with better outcomes for some cancer patients." (PMID 37240071, 2023).
infection (3 papers, 2013 to 2024). The state of being infected such as from the introduction of a foreign agent such as serum, vaccine, antigenic substance or organism. "In this context, patients with variants in BTNL8 may present with unresolved inflammation due to increased intestinal permeability and gut dysbiosis upon infection leading to systemic inflammation resulting in MIS-C." (PMID 39576310, 2024).
infectious disease (1 paper, 2024). A disorder directly resulting from the presence and activity of a microbial, viral, or parasitic agent in humans. "Finally, BTNL8 variation has not previously been associated with an infectious disease." (PMID 39576310, 2024).
BTNL8 also shares sentences with these, for which no sentence is quoted: ulcerative colitis (2 papers); autoimmune disease (1); bacterial infections (1); Immunodeficiency (1); polyendocrinopathy (1); squamous intraepithelial lesions (1).